SNORA77 (small nucleolar RNA, H/ACA box 77)
Synonyms: ACA63; SNORA77A
Gene: Small nucleolar RNA gene on chromosome 1 (203,729,581 to 203,729,705, forward strand). Ensembl gene ENSG00000221643.
Gene Ontology:
Biological process: RNA processing
Cellular component: nucleolus
Homologues: Orthologues: chimpanzee SNORA77 (99% identical), rat Snora77b (82% identical), mouse Gm25777 (81% identical), zebrafish SNORA77B (50% identical). Paralogues in human: SNORA77B (93% identical).